IFNG (interferon gamma)
Diseases named in the same sentence as IFNG in open-access papers (continued):
Sharing a sentence is not in itself a finding about the gene and the disease.
Erythema (20 papers, 2010 to 2025). Redness of the skin, caused by hyperemia of the capillaries in the lower layers of the skin. "Polymorphisms in DNA repair genes (e.g., XRCC2, ERCC2, and ERCC1) and inflammatory mediators like IFNG were most linked to acute adverse effects, including erythema, desquamation, and oedema." (PMID 40507362, 2025). "Remarkably, IFNγ-sEVs alleviated the weight loss and disease severity including thickness, erythema, and scales of skin lesions following treatment." (PMID 35359454, 2022). "IFNγ-MSC-sEVs reduced thickness, erythema, and scales of skin lesions, exhausted Th17 cells, increased Th2 cells, and reduced inflammatory cytokines.IFNγ-MSC-sEVs significantly improved the delivery efficiency and stability of ASO-210." (PMID 41007656, 2025). "Seven recombinant proteins showed greater erythema as compared to the reference PPD lot 9801 in paired guinea pigs and were able to stimulate interferon-gamma production in blood from Johne’s positive animals." (PMID 27136199, 2016). "On the other hand, in EM, infection or drug exposure leads to the excessive expression of inflammatory mediators, such as interferon-gamma (IFN-γ), tumor necrosis factor-alpha (TNF-α), perforin, and granzyme B, resulting in severe skin inflammation, erythema, and epidermal destruction." (PMID 40104458, 2025).
glaucoma (20 papers, 2009 to 2025). Increased pressure in the eyeball due to obstruction of the outflow of aqueous humor. "Monokine induced by interferon-gamma (MIG) exhibited a potential association with an increasing risk of glaucoma (OR: 1.0009, 95% CI: 1.0002–1.0015, p = 0.0085)." (PMID 38327497, 2024). "Oxidative stress also can enhance production of several cytokines, including interleukins, interferon-gamma, and tumor necrosis factor alpha, which contributes to the axonal injury in glaucoma, and the excess production of exfoliative material." (PMID 33352680, 2020). "Elevated levels of TNFα, IFNγ, IL17A, and TGFβ are observed in PACG, which is in alignment with previous reports on glaucoma." (PMID 39184151, 2024). "Similarly, elevated levels of IL-5, IL-12, IL-15, interferon-gamma (IFN-γ), and monocyte inflammatory protein-1α (MIP-1α) have been detected in the aqueous humor of glaucoma patients." (PMID 38327497, 2024). "Aqueous obtained from the glaucoma patients showed increased concentration of interleukin (IL)-9 (p=0.032), IL-12 (p=0.003), interferon (IFN)-α (p=0.034), IFN-γ (p=0.002), monokine induced by interferon-gamma (MIG or CXCL9) (p=0.006), and IL-10 (p=0.050), compared to the cataract group." (PMID 22355254, 2012).
measles (20 papers, 2010 to 2025). A highly contagious viral infection caused by the measles virus. "The SNPs in genes controlling cytokine production, e.g., the interferon gamma (IFN-γ), were revealed, which affect the mode and strength of measles-induced immunity." (PMID 36851738, 2023). "Interferon-gamma (IFNg+) is a potent antiviral cytokine that is essential for cytotoxic T cell-mediated elimination of measles, mumps, and rubella viruses and the establishment of antiviral immunity." (PMID 36457491, 2022). "This is because breast-feeding is generally known to positively modulate response to vaccines (measles, mumps, rubella) through significant developmental changes in Th-1 pipeline response (CD81 T cells, natural killer cells, and mitogen-induced IFNg), as compared to formula-fed infants." (PMID 27656883, 2016).
nasopharyngeal carcinoma (20 papers, 2009 to 2025). A carcinoma arising from the nasopharyngeal epithelium. "Replication-defective adenovirus encoding human IFNγ (Ad-IFNγ) was evaluated in nasopharyngeal carcinoma (NPC) cell lines in vitro and in the xenograft model." (PMID 36140243, 2022). "So IFN-γ gene therapy by a replication defective adenovirus encoding the human IFN-γ (Ad-IFNγ) is likely a potential novel therapeutics on comprehensive therapy of nasopharyngeal carcinoma." (PMID 23272637, 2012). "In this paper, we tried to develop IFN-γ gene therapy by a replication defective adenovirus encoding the human IFN-γ (Ad-IFNγ), and evaluate the antitumoral effects of Ad-IFNγ on nasopharyngeal carcinoma (NPC) cell lines in vitro and in xenografts model." (PMID 23272637, 2012). "In this study, we reported that adenovirus-mediated IFN-γ gene transfer (Ad-IFNγ) inhibited tumor growth of human nasopharyngeal carcinoma (NPC) cells." (PMID 23272637, 2012). "We evaluated the effects of Ad-IFNγ on the proliferation of nasopharyngeal carcinoma (NPC) cells by MTT assay after 72 h after Ad-IFNγ infection." (PMID 23272637, 2012). "The results of the present study indicate that Ad-IFNγ likely performs potent anti-nasopharyngeal carcinoma effects by inhibiting cell proliferation, inducing G1 phase arrest and cell apoptosis." (PMID 23272637, 2012). "Ad-IFNγ efficiently expressed human IFN-γ in nasopharyngeal carcinoma cells in vitro and in vivo, and exhibited strong antiproliferative effects." (PMID 23272637, 2012). "Our laboratory has investigated the potential effect of minicircle-mediated IFNγ gene therapy in human nasopharyngeal carcinoma." (PMID 21573215, 2011). "We previously found that r-hu-IFNγ exerts a potent anti-tumor effect on human nasopharyngeal carcinoma xenografts in vivo." (PMID 19216804, 2009). "Interestingly, Liu and colleagues observed NLRC5-mediated transactivation of endogenous BTN2A1 only upon EBV-reactivation, which also leads to IFNγ upregulation in nasopharyngeal carcinoma cells." (PMID 39035010, 2024). "Also in another EBV-associated tumor, the nasopharyngeal carcinoma (NPC), the EBV-induced latent membrane protein 1 (LMP1) and IFNγ, upregulated PD-L1 expression through AP-1, STAT3 and NF-κB pathways." (PMID 31340499, 2019). "Previous studies have demonstrated the inhibition of IFNγ-dependent phosphorylation of STAT1 by butyrate, in a nasopharyngeal carcinoma model." (PMID 30619249, 2018). "To evaluate the capability of Ad-IFNγ expressed transgenic product in nasopharyngeal carcinoma (NPC) cells, we firstly investigated IFNγ mRNA levels in CNE-2 cells after Ad-IFNγ infection at different multiplicities of infection (MOIs) at different time." (PMID 23272637, 2012). "Our previous study has demonstrated that transfer of human IFNγ gene into nasopharyngeal carcinoma (NPC) by using a novel nonviral vector, minicircle (mc), under the control of cytomegalovirus (CMV) promoter was effective to inhibit tumor growth." (PMID 21573215, 2011).
oral cancer (20 papers, 2014 to 2025). "TrpRS expression and secretion were notably increased in interferon-gamma (IFN-γ)-treated oral cancer cells compared with control cells." (PMID 26110569, 2015). "Moreover, phosphorylation of protein kinase C delta PKC-delta, Janus kinase 1 (JAK1), and Janus kinase 2 (JAK2), which are the upstream activators of STAT1 are also inhibited by EGCG in interferon gamma (IFNγ)-stimulated oral cancer cells." (PMID 32290543, 2020).
ovarian tumor (20 papers, 2011 to 2025). "Cluster B was mainly involved in Reactome pathways, such as antigen processing cross‐presentation, regulation of IFNG signalling, pyroptosis, ovarian tumour domain proteases and interferon signalling." (PMID 40289505, 2025). "Washing platelet-cloaked ovarian tumour cells to remove the platelet releasate partially restored NK cell activity and IFNγ production." (PMID 30908480, 2019). "Two functions (cell-to-cell signaling and interaction, and cellular growth and proliferation, and two upstream regulators (TGFB1 and IFNG) were shared between differentially expressed genes in the isogenic cell lines and differentially expressed genes in BRCA1-deficient vs. normal ovarian tumors." (PMID 31840082, 2019). "Coculture of the human CAR T cells with SKOV3 ovarian tumor cells which are NGcGM3+in vitro revealed highest target cell killing by CAR h2 engineered T cells as evaluated in an IncuCyte assay, but highest IFNγ production by CAR h3 T cells." (PMID 35990626, 2022).
steatosis (20 papers, 2016 to 2025). Increased lipid within the cytoplasm of cells. "On the other hand, 25IM diet improved DI histology, but showed enterocyte steatosis in PC, increased pro-inflammatory cytokine IFNγ in DI and reduced IgM in DI." (PMID 33717079, 2021). "In summary, we described a humanized mouse model for diet-induced NAFLD and showed that subsets of CD4+ T cells, specifically IL-17A-secreting Th17 and IFNγ -secreting Th1, play a key role in the progression of steatosis to fibrosis." (PMID 33013934, 2020). "In the case of BSFL paste diets, 3.7IP diet caused mild inflammatory changes in DI, reduced DI IgM and skin mucus IgD and IFNγ, and tend to increase plasma AST and CK, although it reduced enterocyte steatosis in PC." (PMID 33717079, 2021). "This regulation induces the production of various pro-inflammatory cytokines, such as TNF-α, interferon gamma (IFN-γ), and IL-1β, which are critically regulated hepatic inflammation, steatosis, fibrosis, and HCC." (PMID 32143357, 2020). "The total number of IFNγ producing lymphocytes was unaltered between Atg7f/f and Lck-Cre Atg7f/f mice, suggesting that Atg7 deficiency in T cells causes an increase in the percentage of hepatic IFNγ producing T cells but not in the total number of IFNγ producing cells prior to steatosis development." (PMID 30619297, 2018). "Their concentration differences were statistically significant in comparison to patients with simple steatosis (IL-4 and IL-17) or to both groups of noncirrhosis NAFLD (IFNγ)." (PMID 38015590, 2023).
acne (19 papers, 2014 to 2025). An inflammatory process of the sebaceous glands which is characterized by comedones, nodules, papules and/or pustules on the skin. "Different strains of C. acnes can induce varying immune responses; acne-associated strains trigger pro-inflammatory cytokines like IFNγ and IL-17, whereas health-associated strains promote the production of anti-inflammatory IL-10." (PMID 38791344, 2024). "This review highly recommended further association studies for the candidate genes including IL6, FAS, and IFNG to identify the genetic variants playing unknown roles in the pathogenicity of acne vulgaris and receiving medications." (PMID 37228537, 2023). "Notably, IFNG had the lowest binding energy among all docking groups, constituting the most stable conformation, which provides a basis for future applications of IFNG in the treatment of common acne." (PMID 39552028, 2025). "acnes phylotypes induced distinct cytokine patternsin vitro in peripheral blood mononuclear cells from healthy individuals, including higher levels of inflammatory interferon-gamma (IFN-γ) and IL-17, suggesting a mechanism of inducing acne via both Th1 and Th17 pathways." (PMID 30613388, 2018).
acute lymphoblastic leukemia (19 papers, 2015 to 2025). Leukemia with an acute onset, characterized by the presence of lymphoblasts in the bone marrow and the peripheral blood. "Of note, whereas this intrinsic capacity of enhanced IFNγ production after in vivo IL pre-activation and re-stimulation could be transferred to the next generation of NK cells and was associated with prolonged survival of the mice with acute lymphoid leukemia." (PMID 27816971, 2016). "In addition, baicalin reduced the survival of peripheral blood leukocytes (PBLs) in individuals suffering from acute lymphoblastic leukemia (ALL), increased IFNγ production in PBLs and decreased the production of TNFα and IL-10 in bone marrow cells (BMCs) in ALL patients." (PMID 39911847, 2025). "Together, these findings argue strongly that in vivo IL pre-activation and re-stimulation is capable to induce memory-like NK cells as observed previously in vitro, which are effective against acute lymphoblastic leukemia, likely via NKG2D-dependent IFNγ production, in intact animals." (PMID 27816971, 2016).
aspergillosis (19 papers, 2012 to 2025). Aspergillosis is an infection, growth, or allergic response caused by the Aspergillus fungus. "Likewise, in a murine model of influenza-associated pulmonary aspergillosis, excessive IFNγ production was shown to have resulted in defective Th17-driven immune responses and impaired macrophage function, and that IFNγ ablation promoted improved disease outcomes." (PMID 41285788, 2025). "In a model of aspergillosis, our recent studies also revealed that neutrophils can be a source of IFNγ during pulmonary fungal infection." (PMID 39324785, 2024). "Since clinical and radiographic findings were suggestive of ongoing aspergillosis, interferon gamma (IFN-γ) 200 mcg subcutaneously, three times a week was initiated and continued for six weeks." (PMID 23259133, 2012). "However, we did not observe high-level IL-12 production by cDC2s in the context of stimulation with fungal-derived ZYM, and it remains unclear whether they contribute to priming IFNγ production in the context of pulmonary aspergillosis via other mechanisms." (PMID 40503945, 2025).
autoimmune myocarditis (19 papers, 2011 to 2025). Autoimmune myocarditis is an autoimmune disease that affects the heart. "In experimental autoimmune myocarditis model (EAM) using myocardiotogenic peptide derived from alpha-cardiac myosin heavy chain accompanied for 62 days, IFNγ presented a protective role." (PMID 26592184, 2015).
E. coli infection (19 papers, 2012 to 2025). "We showed that during Lm infection, IFNγ production and cytotoxic activity were severely impaired in NK cells compared to E. coli infection." (PMID 22912878, 2012).
esophageal cancer (19 papers, 2011 to 2025). A primary or metastatic malignant neoplasm involving the esophagus. "Further study is required to determine the significance of endothelial and IFNγ-related biomarkers in esophageal cancer." (PMID 39516370, 2024). "In terms of IFNG, sensitivity to expression levels is evident, as it shows protective trends in esophageal carcinoma (ESCA) and KIRC, yet poses risks in BRCA." (PMID 39635438, 2024). "For instance, IFNγ serum levels in esophageal cancer were reported to correlate with acute organ toxicity, whilst we were unable to reliably detect them at all at the onset of CRT." (PMID 27589568, 2016). "In the present study, an analysis of Kyn production demonstrated that IDO enzymatic activity was only present in the esophageal cancer cell lines treated with IFNγ, and western blot also confirmed the finding." (PMID 22013481, 2011).
Fever (19 papers, 2012 to 2026). Body temperature elevated above the normal range. "Participants with fever, anosmia, or aguesia were significantly more likely to have a positive IFNγ ELISpot." (PMID 38686954, 2024). "Fever was induced using turpentine, an exogenous pyrogen that stimulates endogenous pyrogens such as TNF-α, interferon-gamma (IFN-γ), IL-1β, and IL-6 to initiate the synthesis of PGE2." (PMID 41245555, 2025). "Moreover with pPB- and IFNγ loaded intravenously injected HSA, the IFNγ-loaded pPB-liposomes were as efficient as high dose systemic IFNγ but lacked the unwanted side effects of the systemic treatment like fever and leukopenia." (PMID 32899119, 2020).
Lewis lung carcinoma (19 papers, 2009 to 2025). "In this study, we found that treatment of Lewis lung carcinoma transplants with cisplatin often caused IFNγ-dependent tumour vascular damage." (PMID 37056922, 2023). "T cells such as interferon-gamma (IFN-γ) producing CD4(+) and CD8(+) T cells, were increased by TCS in the 3LL Lewis lung carcinoma tumor model." (PMID 32182799, 2020).
Lyme disease (19 papers, 2010 to 2026). Lyme disease (named after the towns in the USA where the disease was first identified) is a bacterial infection caused by Borrelia burgdorferi. "Lyme disease has been associated with the proinflammatory cytokines Interleukin-6, Interleukin-8, Interleukin-12, Interleukin-18 and interferon-gamma; the chemokines CXCL12, CXCL13 and CCL19 and increased levels of proinflammatory lipoproteins." (PMID 30149626, 2018). "IFNγ, a protective cytokine against cardiac inflammation during Lyme borreliosis, represses MCJ transcription in macrophages." (PMID 26419808, 2015). "A study performed in the years 2002 to 2004 showed a limited use of ELISPOT for the diagnosis of Lyme disease due to high IFNγ secretion by cells from non-infected individuals." (PMID 31443439, 2019).
vasculitis (19 papers, 2012 to 2025). "One hypothesis is that CAR T cell activation in the CNS or meninges could cause a lymphocytic uveitis or vasculitis in ocular tissues; another is that the high cytokine levels (IL-6, IFNγ, etc.)disturb the ocular microenvironment." (PMID 41568391, 2025). "Interestingly, the genes associated with interferon-gamma (IFN-γ)-mediated signaling pathway are highly enriched in both PR3-ANCA and MPO-ANCA vasculitis-associated SNPs (e.g., yellow nodes in the PPI networks)." (PMID 30795559, 2019). "Studies conducted on cases of vasculitis have demonstrated the multinucleated giant cells and other CD68 positive macrophages as sources of vascular endothelial growth factor (VEGF) and interferon gamma, both of which are mediators of angiogenesis." (PMID 33722245, 2021).
viral hepatitis (19 papers, 2007 to 2023). An acute or chronic inflammation of the liver parenchyma caused by viruses. "In conclusion, we demonstrated that endogenous IL-33 had multifaceted immunoregulatory effect during viral hepatitis via induction of IFNγ, survival effect on immune cells, and infiltration of neutrophils in the liver." (PMID 28607531, 2017). "Here, infecting wild-type (WT) and IL-33-deficient mice (IL-33 KO) with L2-MHV3, we showed that the alarmin IL-33 ameliorated the L2-MHV3-mediated liver injury through the regulation of IFNγ expression, survival effect on immune cells, and neutrophil infiltration in viral hepatitis." (PMID 28607531, 2017). "Therefore, we could not exclude the possibility that targeting the PD-1 pathway could boost recall IFNγ responses of HIV-uninfected persons, particularly those with factors that are known to induce T cell exhaustion, such as viral hepatitis or aging." (PMID 36851089, 2023).
bladder tumor (18 papers, 2012 to 2025). "Response to treatment was significantly associated with elevated urinary T cells including CD8+ and IFNγ+ CD4+ T cells, suggesting potential reinforcement of immune responses by neoadjuvant αPD-1 and αCTLA-4 against bladder tumor cells." (PMID 38784962, 2024). "This study used a curated gene set representing the in vitro response of human urothelium to IFNγ to provide new understanding of signalling in bladder tumours." (PMID 36358715, 2022). "We noted that both IFNγ and GzmB production were drastically reduced in CD8+ T cells from tumor site as compared to their PBMC counterpart, strongly suggesting the functional impairment of T cells at the bladder tumor site." (PMID 37566017, 2023).